OR2T12 (olfactory receptor family 2 subfamily T member 12)
Description:
Odorant receptor.
Synonyms: OR1-57
Tractability: Antibody: UniProt places it where antibodies can reach, with medium confidence; UniProt predicts a signal peptide or a membrane-spanning region; its Gene Ontology location is reachable by antibodies, with medium confidence.
Gene: Protein-coding gene on chromosome 1 (248,290,139 to 248,303,424, reverse strand). Ensembl gene ENSG00000177201.
Subcellular location: Cell membrane
Pathways (Reactome):
Sensory Perception: Expression and translocation of olfactory receptors
Gene Ontology:
Molecular function: olfactory receptor activity; G protein-coupled receptor activity
Biological process: detection of chemical stimulus involved in sensory perception of smell; G protein-coupled receptor signaling pathway
Cellular component: plasma membrane; membrane
Genetic constraint (gnomAD): Loss-of-function variants: 0 observed, 0.34 expected, observed/expected ratio (o/e) 0, 90% interval 0 to 1.86. That is too few expected variants to judge how well the gene tolerates losing a copy. Missense variants: 306 observed, 358.21 expected, observed/expected ratio (o/e) 0.85, 90% interval 0.78 to 0.94. Synonymous variants: 118 observed, 138.23 expected, observed/expected ratio (o/e) 0.85, 90% interval 0.73 to 1.
Homologues: Orthologues: dog OR2T13 (75% identical), dog OR2T20 (75% identical), dog OR2T15 (75% identical), dog OR2T24 (75% identical), mouse Or2t44 (72% identical), rat Olr1454 (71% identical), rat Or2t44 (70% identical), rat Or2t44b (70% identical). Paralogues in human: OR2T33 (95% identical), OR2T8 (88% identical), OR2M2 (54% identical), OR2M3 (54% identical), OR2M5 (54% identical), OR2M7 (54% identical), OR2M4 (53% identical), OR2V2 (53% identical), OR2T1 (53% identical), OR2V1 (53% identical), OR2T2 (52% identical), OR2T27 (52% identical), and 80 more.